BANCR (BRAF-activated non-protein coding RNA)
Diseases named in the same sentence as BANCR in open-access papers (continued):
Sharing a sentence is not in itself a finding about the gene and the disease.
tumor (continued). "On the other hand, overexpression of BANCR reduced tumor growth in BALB/c PTC models." (PMID 38092752, 2023). "After tumor removal, plasma BANCR levels revert to the levels observed in healthy individuals." (PMID 35241975, 2022). "Given the multiple mechanisms of action known for lncRNAs, it is not surprising that the same lncRNAs may exert dual functions in cancer, acting as either tumor suppressors or oncogenes, depending on the cancer type (H19, BANCR, TINCR, MALAT, XIST)." (PMID 35159386, 2022). "In papillary thyroid carcinoma, lncRNA BANCR is responsible for maintaining stemness and tumor growth via the c-RAF/MEK/ERK pathway; additionally, it is observed to influence the expression of CSC markers LGR5 and EpCAM, this eventually leads to tumor development." (PMID 36359888, 2022). "On the other hand, BANCR has tumor suppressor effects in a number of cancers." (PMID 34409032, 2021). "In samples harboring BRAF V600E mutation, up-regulation of BANCR has been correlated with lymph node involvement, while in BRAF V600E negative samples, over-expression of this lncRNA has been linked with invasion of tumor to thyroid capsule." (PMID 34409032, 2021). "Interestingly, combined treatment with rutin and SO led to more significant inhibition of tumor volume, BANCR, and OLR1 levels, and promotion of miRNA-590-5P expression." (PMID 34512168, 2021). "In other words, expression levels of target miRNAs or transcription factors in each tissue might define the oncogenic or tumor suppressor role of BANCR." (PMID 34409032, 2021). "In this regard, lncRNAs may be considered as tumor-promoting (e.g., BANCR), when their sponging activity triggers the increase of oncogenes expression, or tumor suppressors (e.g., MEG3), when they positively regulate the expression of tumor suppressor genes." (PMID 34638331, 2021). "For BANCR, some researchers have identified its influence in tumor invasion and migration." (PMID 34745939, 2021). "Animal studies have shown the impact of modulation of BANCR expression on tumor growth." (PMID 34409032, 2021). "Radiation therapy functions through BANCR up-regulation to inhibit tumor growth." (PMID 34409032, 2021). "Moreover, BANCR depletion triggered an elevation of miR-203 expression and a reduction of CSE1L level, suggesting that BANCR downregulation repressed tumor growth and enhanced ADR sensitivity via regulation of miR-203/CSE1L pathway in vivo." (PMID 30144787, 2018). "Additionally, an inverse correlation was observed between miR-203 and BANCR or CSE1L in CRC tumor tissues." (PMID 30144787, 2018). "Moreover, we further demonstrated that BANCR and CSE1L expressions were decreased, while miR-203 expression was increased in tumor tissues derived from sh-BANCR-transfected HCT116 cells." (PMID 30144787, 2018). "Next, in vivo assays further revealed that ADR injection or BANCR knockdown curbed tumor growth, and BANCR silencing could enhance ADR-induced anti-tumor effect in mouse xenograft model of CRC." (PMID 30144787, 2018). "On the contrary, BANCR was reported to promote tumor growth in various cancers." (PMID 30200918, 2018). "BANCR knockdown also inhibited tumor growth and enhanced ADR sensitivity in CRC mice model." (PMID 30144787, 2018). "Furthermore, knockdown of BANCR inhibits tumor cell growth and induces cell cycle arrest at G0/G1 phase through the reduction of cyclin D1." (PMID 29416703, 2018). "Our results suggest that PTC tumors with high BANCR levels are more differentiated than those with low BANCR levels and that BANCR may function as a tumor suppressor in PTC." (PMID 27462868, 2017). "Our results indicate BANCR levels are lower in PTC tumor tissues than control tissues." (PMID 27462868, 2017). "Ectopic expression of BANCR shown in multiple cancer types may due to tumor heterogenicity; these findings motivated us to explore the effects of BANCR in PTC and to delineate the associated mechanisms." (PMID 27462868, 2017).
tumor (continued). "In this study, we report that BRAF-activated BANCR may function as a tumor suppressor via the ERK/MAPK signaling pathway in PTC." (PMID 27462868, 2017). "In xenograft mouse models, K1 cells overexpressing BANCR exhibited lower tumor proliferation." (PMID 27462868, 2017). "Finally, BANCR overexpression dramatically inhibited tumor growth from PTC cells in xenograft mouse models." (PMID 27462868, 2017). "Furthermore, Ki67+ tumor cell number as measured by IHC is reduced and BANCR expression measured by qPCR is increased in the K1-BANCR group compared with the control group." (PMID 27462868, 2017). "In addition, we used the univariate Cox regression model analysis and found that the tumor size (P = 0.012), depth of invasion (P = 0.025), lymph node metastasis (P < 0.001), and lncRNA BANCR expression (P = 0.001) were the prognostic factors of CRC patients." (PMID 28969673, 2017). "In addition, High BANCR expression was closely correlated with higher tumor grade, larger tumor size, more serious venous infiltration and TNM stage." (PMID 29212285, 2017). "We also found that lower BANCR expression correlates with advanced tumor stage and size." (PMID 27462868, 2017). "The differential expression and effects of BANCR in different types of cancer may be attributed to the variation of local tumor microenvironment and molecular pathways." (PMID 28969673, 2017). "In addition, lncRNA BANCR exerts tumor-suppressive functions in NSCLC cells, while HOTAIR, MALAT1, LUADT1 and AFAP1-AS1 et.al exert oncogenic function in NSCLC." (PMID 26840083, 2016). "In these tumors, BANCR regulated cell proliferation, migration, and invasion and may serve as a potential oncogene or a candidate tumor suppressor." (PMID 26758762, 2016). "Our study also showed that high BANCR levels correlated tumor progression and poor prognosis." (PMID 26758762, 2016). "When BANCR expression was strengthened by gain-of-function, tumor growth depressed and vice versa." (PMID 27686732, 2016). "We found that high BANCR expression levels were closely correlated with high tumor grade (P = 0.007), large tumor size (P = 0.003), venous infiltration (P = 0.001), and advanced tumor, node, and metastasis (TNM) stage (P = 0.002)." (PMID 26758762, 2016). "qRT-PCR analysis of BANCR expression was then performed in selected tumor tissues." (PMID 25928067, 2015). "We next determined whether BANCR expression influenced tumor-like characteristics, such as cell cycle progression and apoptosis." (PMID 25928067, 2015). "Nude mice were used to examine the effects of BANCR on tumor cell metastasis in vivo." (PMID 24655544, 2014). "Maternally expressed gene 3 (MEG3), GAS6-AS1 (growth-arrest-specific gene 6 antisense 1 RNA) and BANCR (BRAF activated non-coding RNA) are tumour-suppressor lncRNAs, whose down-regulation may promote the development of NSCLC." (PMID 25297942, 2014). "Therefore, BANCR may function as an oncogene or tumor-suppressor gene in a context-dependent manner." (PMID 34409032, 2021). "Therefore, the expression level of BANCR could be used to evaluate the prognosis of tumor patients in most cancers." (PMID 32907530, 2020). "In addition, maternally expressed genes 3 (MEG3), GAS6-AS1, BANCR are tumor suppressor lncRNAs, and their down-regulation may promote the initiation and development of NSCLC." (PMID 30840927, 2019). "The present study revealed that BANCR was overexpressed in BC cell lines and tissues, and could promote the clinical progression of disease, including increases in tumor size, lymph node metastasis and tumor-node-metastasis stage." (PMID 30459529, 2018). "BANCR could repress proliferation of tumor cells both in vitro and in vivo." (PMID 24967732, 2014). "Taken together, the results of in vivo experiments further supported that BANCR OE inhibited G6PD activity through post-transcriptional regulatory mechanisms, thereby limiting the tumor growth of ccRCC cells." (PMID 39894218, 2025).
tumor (continued). "Subsequent experiments demonstrated a significant inhibition of tumor growth in vivo upon overexpression of BANCR, and G6PD played a pivotal role in mediating the tumor-suppressive effect of BANCR in ccRCC cells." (PMID 39894218, 2025). "BANCR and G6PD were mainly coexpressed and colocalized in the cytoplasm of cell lines and ccRCC tumor cells, which not only confirmed the ectopic expression of G6PD in ccRCC but also suggested a potential interaction between BANCR and G6PD." (PMID 39894218, 2025). "Microarray analyses revealed several differentially expressed lncRNAs; among them, five novel lncRNAs, TINCR, CCAT2, AOC4P, BANCR, and LINC00857, were detected in tumor tissue samples and pre and post-operative plasma." (PMID 37670949, 2023). "Increased expression of BANCR was positively correlated with FIGO stage, tumor grade, myometrial invasion and lymph node metastasis in patients with EC." (PMID 30781521, 2019). "Tumor suppressive lncRNAs (GAS5, MEG3, FER1L4 and LINC00672) and oncogenic lncRNAs (CCAT2, BANCR, NEAT1, MALAT1, H19 and Linc-RoR) have been identified as key regulators of the established tumor suppressor or oncogenic pathways in EC." (PMID 30781521, 2019). "The present study revealed that LncRNA BRAF-regulated LncRNA 1 (BANCR) was overexpressed in BC cell lines and tissues, and could promote the clinical progression of disease, including increases in tumor size, lymph node metastasis and tumor-node-metastasis stage." (PMID 30459529, 2018). "Results showed that BANCR and CSE1L expressions were both significantly upregulated in CRC tumor tissues (n=32) compared with adjacent normal tissues (n=32)." (PMID 30144787, 2018). "In the present study, we firstly demonstrated that BANCR and CSE1L expressions were both upregulated in CRC tumor tissues and cells, consistent with earlier studies." (PMID 30144787, 2018). "Results showed that ADR injection or BANCR knockdown curbed tumor growth, and BANCR silencing enhanced ADR-induced anti-tumor effect in vivo." (PMID 30144787, 2018). "Therefore, BANCR may be a novel tumor biomarker and potential therapeutic target for ESCC patients." (PMID 29212285, 2017). "Therefore, BANCR clearly has a role in the incidence and progression of PTC through modifying several tumor-related signaling pathways, including MAPK, but its ultimate effect is likely to be dependent on other regulatory mechanisms." (PMID 38137560, 2023). "High BANCR expression predicts poor survival outcomes, advanced TNM stages, positive lymph node metastasis, poor histological grade and earlier distant metastasis of tumor cells." (PMID 32907530, 2020). "Tumor suppressive lncRNAs (GAS5, MEG3, FER1L4 and LINC00672) and oncogenic lncRNAs (CCAT2, BANCR, NEAT1, MALAT1, H19, Linc-RoR, TUG1, TDRG1 and PCGEM1) may be a few such examples." (PMID 30781521, 2019). "In this study, we found that BANCR and CSE1L expressions were upregulated in CRC tumor tissues." (PMID 30144787, 2018). "BANCR expression was elevated in GC tissues compared to matched non-cancerous tissue but downregulated in 113 NSCLC tumor tissues compared to match normal samples." (PMID 27686732, 2016). "Additionally, Spearman’s test found that there existed a negative correlation between miR-203 and BANCR or CSE1L in CRC tumor tissues." (PMID 30144787, 2018). "However, lncRNA BANCR expression did not correlate with other clinicopathological features, such as age (P = 0.430), gender (P = 0.558), tumor size (P = 0.556), differentiation (P = 0.672), venous invasion (P = 0.115), depth of invasion (P = 0.115), and location (P = 0.846)." (PMID 28969673, 2017). "Firstly, RT-qPCR assay was performed to measure expression patterns of BANCR and CSE1L in 32 pairs of CRC tumor tissues and adjacent normal tissues." (PMID 30144787, 2018).
cancer (33 papers, 2014 to 2025). A tumor composed of atypical neoplastic, often pleomorphic cells that invade other tissues. "Meanwhile, BRAF-activated noncoding RNA (BANCR) has emerged as a crucial regulatory factor linked to various cancers." (PMID 39894218, 2025). "In this review, we will discuss the current knowledge about the functions and underlying mechanisms of BANCR in various cancers’ progression." (PMID 29212285, 2017). "Analysis of 410 patients from three eligible studies demonstrated association between BANCR levels and cancer patients with DM." (PMID 28009984, 2017). "In general, the high expression of BANCR is significantly associated with shorter OS and poor clinical prognosis, and BANCR may be treated as a biomarker and therapeutic target for cancer." (PMID 32907530, 2020). "The results showed that elevated BANCR expression was associated with unfavorable prognosis for most cancer patients, and BANCR could serve as a promising therapeutic target and independent prognostic predictor in most of cancer types." (PMID 32907530, 2020). "PTC patients had higher and lower rates of elevated BANCR and miR-9 expression, respectively, in carcinoma vs. adjacent normal tissue, and there was a negative association that was observed between BANCR and miR-9 expression in carcinoma." (PMID 32593310, 2020). "Patients with BRAFV600E mutation have a higher rate of BANCR overexpression and tended to have a lower rate of miR-9 overexpression (P = 0.057), and a negative association was observed between BANCR and miR-9 expression in carcinoma tissue." (PMID 32593310, 2020). "Notably, tumors with larger dimensions, which signify their higher burden, or more advanced stages have been shown to have more prominent reduced levels of BANCR indicating the importance of BANCR as a suitable diagnostic marker for early stages of this type of cancer." (PMID 34409032, 2021). "The expression pattern of BANCR varies across different cancer types, exhibiting apparent duality in its function." (PMID 39894218, 2025). "Given that G6PD is one of the primary regulatory factors of ccRCC metabolic disorders and can be manipulated by BANCR, it is currently unclear to what extent BANCR is involved in the metabolic reprogramming of ccRCC or other cancers." (PMID 39894218, 2025). "In recent years, BANCR has been found to play a regulatory role in the proliferation, metastasis, and invasion of various malignant tumors such as gastric cancer, hepatocellular carcinoma, and thyroid adenocarcinoma." (PMID 37998732, 2023). "NF-κB1 and miR-9 are involved in the process of BANCR promoting cancer cell proliferation and inhibiting apoptosis." (PMID 36447000, 2023). "The effects of BANCR on cancer cell migration are mediated through induction of EMT via an MEK/ERK-dependent route." (PMID 34409032, 2021). "For example, BANCR was previously identified as a cancer-promoting lncRNA and was also significantly related to the pathogenesis of multiple cardiovascular diseases." (PMID 34671599, 2021). "An experiment in the uterine leiomyoma has indicated the effect of anti-cancer agent deoxyelephantopin in down-regulation of a number of oncogenic lncRNAs including BANCR." (PMID 34409032, 2021). "In the present manuscript, we review the investigations related to BANCR expression changes in cancerous cell lines, clinical samples, and animal models of cancer." (PMID 34409032, 2021). "A previous meta-analysis of 11 published papers on 1240 cancer samples has shown lower overall survival of patients who had BANCR over-expression." (PMID 34409032, 2021). "In the present manuscript, we provide an update on investigations related to BANCR expression changes in cancerous cell lines, clinical samples and animal models of cancer." (PMID 34409032, 2021). "Based on the conflicting conclusions, some researchers tried to explore the potential molecular biological mechanisms of BANCR in the occurrence and development of cancer." (PMID 32907530, 2020).
cancer (continued). "In summary, despite serving as both an oncogene and a tumor suppressor gene in different cancers, the pooled results still support the conclusions of most primary studies that have shown that high BANCR expression indicates worse cancer prognosis." (PMID 32907530, 2020). "In summary, the expression level and role of BANCR varies from cancer to cancer, possibly due to the differences between tumors." (PMID 32907530, 2020). "Carcinoma and adjacent normal tissue samples were analyzed for the presence of the BRAFV600E mutation and/or expression of BANCR and miR-9." (PMID 32593310, 2020). "Carcinoma (n = 51) and adjacent normal tissue (n = 31) samples were used to detect expression levels of BANCR and miR-9." (PMID 32593310, 2020). "BANCR expression has been shown to elicit EMT like changes in cancer cells as well as ARPE-19 cells." (PMID 31659187, 2019). "Briefly, the expression of BANCR was obviously down-regulated in 67.7% (42 of 62) cancer tissues compared with adjacent normal renal tissues of ccRCC patients (p < 0.01)." (PMID 30200918, 2018). "lncRNA BANCR has been reported in various cancers, however, its biological functions as well as prognosis value in different cancer patients were contradictory." (PMID 30200918, 2018). "We performed a cumulative meta-analysis to assess the role of BANCR in cancer patient overall survival (OS)." (PMID 28009984, 2017). "LncRNA BANCR expression was significantly increased in cancer tissues compared with the paired adjacent normal tissues (P < 0.001)." (PMID 28969673, 2017). "Here, we focus on the current research on the role of BANCR in the clinical management, progression and molecular mechanisms in human cancer." (PMID 29212285, 2017). "The results showed that MAlAT1 and BANCR had similar trend of expression between the two kinds of cancers." (PMID 28938549, 2017). "Some meta-analyses focused on the association of lncRNAs such as BANCR, HOTTIP, CCAT2, and metastasis as well as prognosis of cancers; all of them were based on the lncRNAs detected in tissues." (PMID 29088881, 2017). "So far, several studies also evaluated the prognostic value of lncRNA BANCR expression and suggested BANCR was an independent prognostic factor in several types of cancer." (PMID 28969673, 2017). "We also used lentiviral vectors to establish PTC cell lines to investigate the effects of BANCR overexpression on cancer cell proliferation, apoptosis, migration and invasion." (PMID 27462868, 2017). "Subgroup analyses in a fixed or random model allowed us to assess the role of BANCR in different cancer types." (PMID 28009984, 2017). "Because the role of BANCR as a molecular biomarker in human cancer was unclear, our study explored the prognostic value of BANCR in cancer patients via a meta-analysis." (PMID 28009984, 2017). "Nevertheless, the complex mechanisms of BANCR involved in cancer development are still in the early stage." (PMID 29212285, 2017). "Compared with pair-matched adjacent normal bladder tissues, the BANCR expression was down-regulated significantly in 64.8 % (35 of 54) of cancer tissues (***P < 0.001)." (PMID 27514530, 2016). "BRAF activated non-coding RNA (BANCR) has been identified to contribute to the progression of some human cancers." (PMID 27514530, 2016). "BANCR expression levels in BC, paired non-cancer tissues and BC cell lines were detected by real-time quantitative RT-PCR (qRT-PCR)." (PMID 27514530, 2016). "The clinical significance of BANCR, and its’ molecular mechanisms controlling cancer cell migration and metastasis are unclear." (PMID 24655544, 2014). "The findings suggested that functional BANCR might become a promising biomarker for cancer diagnosis and prognostic evaluation." (PMID 39894218, 2025). "The ERV-derived lncRNA BANCR is important for the future study of human cancers." (PMID 39408810, 2024).